FNDC1 (fibronectin type III domain containing 1)
Diseases named in the same sentence as FNDC1 in open-access papers:
FNDC1 is named in the same sentence as 55 diseases in open-access papers, as found by Europe PMC text mining. Sharing a sentence is not in itself a finding about the gene and the disease. The quoted sentences say what the papers report.
gastric cancer (10 papers, 2015 to 2026). A primary or metastatic malignant neoplasm involving the stomach. "FNDC1 (fibronectin type III domain containing 1) was found to be related to hypoxia and to be associated with chemoradiation resistance and poor prognosis of gastric cancer, breast cancer, and colorectal cancer by multiple pathways." (PMID 36313435, 2022). "However, recent studies have shown that aberrant expression of FNDC1 is associated with tumorigenesis, for example, in gastric cancer." (PMID 38787238, 2024). "Additionally, high FNDC1 expression was also reported to be associated with poor prognosis in gastric cancer, which is consistent with our findings." (PMID 34968391, 2021). "In contrast, FNDC1 promotes the invasiveness of gastric cancer and correlates with the appearance of peritoneal metastasis." (PMID 38787238, 2024). "FNDC1 was shown to be significantly elevated in diffuse gastric adenocarcinoma, gastric intestinal type adenocarcinoma, gastric mixed adenocarcinoma, gastric adenocarcinoma and gastric cancer from Cho, Wang and DErrico datasets." (PMID 36626432, 2022). "Further, knockdown of FNDC1 was found to inhibit proliferation, invasion and migration of gastric cancer cells, and by modulating the Wnt/β-catenin signaling pathway, FNDC1 may facilitate the EMT of gastric cancer cells." (PMID 38213716, 2024). "However, some genes such as HOXC9, FNDC1, STRA6, KCNE2, PGA3 and KCNJ16 haven’t been reported in gastric cancer and their roles remain unknown." (PMID 25928635, 2015). "In addition, we discovered some novel genes, such as TMEM184A, PSAPL1, KIAA1199, CLRN3 and FNDC1, which have not been reported in gastric cancer previously, and their roles in cancer remain unknown." (PMID 25928635, 2015).
breast carcinoma (6 papers, 2017 to 2023). "Following analysis of the Ma 4 dataset, we discovered that the FNDC1 gene was significantly expressed in 3 different types of breast cancer: ductal breast carcinoma in situ, invasive ductal breast carcinoma (IDC), and IDC epithelia." (PMID 36626432, 2022). "First, breast cancers with highly suspicious calcifications are associated with high levels of mRNA expression of ERBB2 and decreased expression of COL11A1 and FNDC1." (PMID 28900139, 2017). "In addition, high expression of FNDC1 (probe 226930_at, p = 0.019) and the low expression of PDIA3 (probe 227033_at, p = 0.0037), HSPA5 (probe 230031_at, p = 0.0024) and CANX (probe 238034_at, p = 0.0013) were also associated with a worse overall survival in breast cancer patients." (PMID 34885011, 2021). "In our study, breast cancers with suspicious calcifications had low expression of COL11A1 and FNDC1." (PMID 28900139, 2017). "Finally, an independent validation showed FNDC1, A1BG, PDIA3, HSPA5, and calnexin as significant prognostic markers for human breast cancer patients." (PMID 34885011, 2021). "By analyzing heterogeneous intratumor subpopulations and metastatic sites, we demonstrated that FNDC1, A1BG, CANX, HSPA5, and PDIA3 may be key factors to tumor malignancy in a canine model of breast cancer." (PMID 34885011, 2021). "FNDC1 is up-regulated in breast cancers without suspicious calcifications compared to those with highly suspicious calcifications (p = 4.67E-06) and low-to-intermediate suspicious calcifications (p = 0.014)." (PMID 28900139, 2017).
prostate carcinoma (5 papers, 2017 to 2024). A carcinoma that arises from epithelial cells of the prostate gland. "In prostate cancer, hsa-miR-1207-5p is downregulated and associates with the androgen receptor via FNDC1, a protein that contains a conserved protein domain of fibronectin and it is upregulated in this type of cancer." (PMID 38146340, 2023). "In a study on prostate cancer, miR-1207-3p regulated the androgen receptor via FNDC1/fibronectin, demonstrating the promoting effect of FNDC1 on androgen receptor expression." (PMID 38649819, 2024). "The silencing of FNDC1 inhibited the proliferation and migration of prostate cancer cells." (PMID 34968391, 2021). "It has been described that FNDC1 regulates the androgen receptor in prostate cancer." (PMID 31093274, 2019). "On the other hand, FNDC1 expression correlates with aggressive prostate cancer." (PMID 31093274, 2019). "This might suggest a functional role of FNDC1 in IBD, which was until now foremost known for its pathological role in cardiocirculatory disorders and prostate cancer." (PMID 31093274, 2019).
Hypertension (4 papers, 2016 to 2023). The presence of chronic increased pressure in the systemic arterial system. "The existing studies have also displayed that FNDC1 is a pathogenic gene of acute otitis media in children, and has a certain correlation with hypertension." (PMID 36277792, 2022). "Previous studies have also shown that FNDC1 has a certain relationship with hypertension." (PMID 36277792, 2022). "FNDC1 SNPs associated with CHD risk stratified by hypertension vs. non-hypertension and diabetes vs. non-diabetes." (PMID 36277792, 2022). "Thus, C1QTL1/FNDC1 impacts on BP regardless of the salt content and is applicable to human essential hypertension." (PMID 36674778, 2023).
colorectal cancer (3 papers, 2019 to 2022). A primary or metastatic malignant neoplasm that affects the colon or rectum. "OS, DFS, and DSS survival curves of patients with low FNDC1 expression were associated with the long survival time of colorectal cancer patients." (PMID 36626432, 2022). "In comparison to normal tissues, FNDC1 and FNDC3B were highly expressed in colorectal cancer using the Oncomine database." (PMID 36626432, 2022). "We here aim to comprehensively analyze the mRNA expression of FNDC1, FNDC3A, FNDC3B, FNDC4, FNDC5, and GPR116 in nonaffected and affected mucosal samples of patients with IBD or colorectal cancer (CRC)." (PMID 31093274, 2019).
aortic stenosis (2 papers, 2022 to 2023). Aortic valve stenosis is a aortic valve disease caused by the incomplete opening of the aortic valve. "Among these upregulated genes, FNDC1 and MXRA5 have been recently reported as signatures of chondrocyte-mediated valve calcification in aortic stenosis." (PMID 36548025, 2022). "Both FNDC1 and MXRA5 have been identified as novel extracellular matrix (ECM) biomarkers in calcified valves, making them potential targets in the development and progression of aortic stenosis." (PMID 38077583, 2023).
coronary artery aneurysm (2 papers, 2021 to 2022). "In one study, the FNDC1 polymorphism (rs3003174) was associated with coronary artery aneurysm complications in Kawasaki disease." (PMID 36277792, 2022).
diabetes (2 papers, 2019 to 2022). "Coding polymorphisms in the consensus Chr 17 area included those linked to cancer (Fndc1, Tiam2, Zdhhc14 Has1), growth and development (Igf2r, Afdn, Tiam2, T2), immunology or diabetes itself via the energetic electron transfer chain (Tiam2, Pde10A) or basal thermal metabolism." (PMID 31661517, 2019).
Duchenne muscular dystrophy (2 papers, 2025). Duchenne muscular dystrophy (DMD) is a neuromuscular disease characterized by rapidly progressive muscle weakness and wasting due to degeneration of skeletal, smooth and cardiac muscle. "Having observed improvement in pathological phenotype by FNDC1 treatment in mdx mice, we further assessed the effects of FNDC1 on motor performance and muscle function since these are common manifestations of Duchenne muscular dystrophy patients." (PMID 39567831, 2025). "Administration of recombinant FNDC1 mitigated muscle pathology in a Duchenne muscular dystrophy mouse model, implying its therapeutic potential against muscle diseases." (PMID 40641114, 2025). "Furthermore, recombinant FNDC1 treatment ameliorated pathological muscle phenotypes in the mdx mouse model of Duchenne muscular dystrophy." (PMID 39567831, 2025).
inflammatory bowel disease (2 papers, 2021 to 2025). A spectrum of small and large bowel inflammatory diseases of unknown etiology. "FNDC1 was shown to be involved in the pathological changes in inflammatory bowel disease." (PMID 34968391, 2021). "In addition, previous study has shown that FNDC4 and FNDC1, but not FNDC5, are significantly increased in human inflammatory bowel disease, and FNDC4 has been described as an anti-inflammatory factor." (PMID 39567831, 2025).
liver cancer (2 papers, 2022 to 2023). An epithelial or non-epithelial malignant neoplasm that arises from the liver. "With respect to liver cancer, high expression of FNDC1, FNDC3A, FNDC5, and FNDC7 was correlated with better prognosis, but increased expression of FNDC6 and FNDC8 was correlated with poor OS and PFS, respectively." (PMID 36626432, 2022). "FNDC1 High expression was tightly correlated with poor prognosis in ovarian cancer but with good RFS and PFS in liver cancer." (PMID 36626432, 2022).
lung adenocarcinoma (2 papers, 2022). A carcinoma that arises from the lung and is characterized by the presence of malignant glandular epithelial cells. "Conversely, upregulated FNDC1, FNDC4, FNDC5, and FNDC6 were associated with worse survival in patients with lung adenocarcinoma." (PMID 36626432, 2022). "Moreover, we also identified several genes with IDR hotspots, which play important roles in cancer, such as FNDC1 in lung adenocarcinoma and TANC2 in uterine corpus endometrial carcinoma." (PMID 35061901, 2022). "Similarly, taking advantage of the Oncomine database, we obtained relationships between FNDC family expression and lung cancer, which mainly includes lung adenocarcinoma and squamous cell lung carcinoma, but only FNDC1 and FNDC6 displayed significant results under the set thresholds." (PMID 36626432, 2022). "In light of Hou’s analysis, both FNDC1 and FNDC6 were upregulated in squamous cell lung carcinoma, and FNDC6 was significantly increased in lung adenocarcinoma." (PMID 36626432, 2022).
aortic valve calcification (1 paper, 2024). "FNDC1 is a biomarker of aortic calcified valves and interacts with lipid components in plasma to promote the development of inflammatory responses during aortic valve calcification." (PMID 39006834, 2024).
breast tumour (1 paper, 2022). "Mass spectrometric data from 125 breast tumour samples showed CTHRC1, POSTN and MMP13 to all be significantly higher in breast tumour tissue relative to normal while SFRP4 and FNDC1 levels were unaffected." (PMID 36190948, 2022).
cardiomyopathy (1 paper, 2025). A disease of the heart muscle or myocardium proper. "Moreover, the beneficial effect of FNDC1 on ameliorating systemic inflammation might indirectly benefit cardiomyopathy in DMD by reducing inflammatory damage and promoting a favorable cardiac environment as shown in other situations." (PMID 39567831, 2025).
dilated cardiomyopathy (1 paper, 2025). Cardiomyopathy which is characterized by dilation and contractile dysfunction of the left and right ventricles. "Further research is necessary to explore the systemic role of FNDC1 in these directions especially in heart function since DMD patients often die from dilated cardiomyopathy." (PMID 39567831, 2025).
heart failure (1 paper, 2016). Inability of the heart to pump blood at an adequate rate to meet tissue metabolic requirements. "The expression of Ags8/Fndc1 is induced specifically in cardiomyocytes in response to ischemia/hypoxia, but not under other cardiac dysfunctions including prolonged tachycardia, Ang II-infused hypertrophy, and heart failure." (PMID 27064407, 2016).
metastatic cancer (1 paper, 2025). A carcinoma which has spread from the original site of growth to another anatomic site. "The results showed that the expression levels of CLOCK, along with CBX5, CHN1, CNN3, FNDC1, PALLD, and SULF1, were significantly elevated in metastatic cancer tissues compared to primary cancer tissues." (PMID 41350567, 2025).
nephritis (1 paper, 2024). Inflammation of renal tissue. "Collagen alpha-1(II) chain, fibronectin type III domain-containing 1, and tubulointerstitial nephritis antigen-like 1 protein are components of the ECM." (PMID 39519833, 2024).
otitis media (1 paper, 2021). Inflammation of the anatomical structures of the middle ear, which is most often caused by an infectious process. "Furthermore, genome-wide association studies have shown that particular genes, including FNDC1, are associated with otitis media, validating the essential roles of genetics in otitis media-induced hearing loss." (PMID 34912812, 2021).
postmenopausal osteoporosis (1 paper, 2024). Metabolic disorder associated with fractures of the femoral neck, vertebrae, and distal forearm. "FNDC1 expression has been found to be associated with postmenopausal osteoporosis." (PMID 39497989, 2024).
premature ovarian failure (1 paper, 2019). "It positively regulates cell apoptosis by targeting the expression of tumor necrosis factor superfamily member 10 (TNFSF10) and fibronectin type III domain containing 1 (FNDC1) in mice with premature ovarian failure." (PMID 30777008, 2019).
Primary Immunodeficiency (1 paper, 2025). "For FNDC1, significant involvement was observed in the Calcium signaling pathway, Cytokine-Cytokine Receptor Interaction, and Primary Immunodeficiency." (PMID 40901835, 2025).
prostate tumor (1 paper, 2021). "In addition, FNDC1 knockdown inhibited gastric and prostate tumor cell proliferation, invasion and also downregulated the expression of important proteins involved in epithelial-to-mesenchymal transition (EMT), but the mechanisms have still not been elucidated." (PMID 34885011, 2021).
Stroke (1 paper, 2014). Sudden impairment of blood flow to a part of the brain due to occlusion or rupture of an artery to the brain. "Our studies also suggest that the new “stroke genes” Fnbl5, Fndc1, Pcolce, Scpep1, and Igfbp7 induce EC-lumen formation by increasing the stiffness of the ECM and increasing BV elasticity." (PMID 24672479, 2014).
Tetralogy of Fallot (1 paper, 2023). A congenital cardiac malformation comprising pulmonary stenosis, overriding aorta, ventricular septum defect, and right ventricular hypertrophy. "FNDC1 was among the 10 most up-regulated transcripts in patients undergoing repair of tetralogy of Fallot heart tissue, compared with right ventricle donor tissue." (PMID 38077583, 2023).
cancer (19 papers, 2015 to 2025). A tumor composed of atypical neoplastic, often pleomorphic cells that invade other tissues. "FNDC1 - Fibronectin type III domain containing 1 (FNDC1) activates a G-protein signaling cascade that leads to the activation of PI3K/Akt/mToR signaling which leads to cancer growth and proliferation." (PMID 38304289, 2023). "TS-C2 was located between cancer cells and islets and expressed FNDC1 and COL1A1." (PMID 37124494, 2023). "Pan-cancer analysis revealed the expression patterns of FNDC1 and RSPO3 in solid cancers." (PMID 36755806, 2023). "Recent studies have found that FNDC1 also has a role in different diseases including cancer." (PMID 34968391, 2021). "FNDC1, a member of the fibronectin type III domain-containing (FNDC) protein family, was commonly used as a prognostic biomarker for specific cancers." (PMID 38649819, 2024). "The upregulated expression of FNDC1 has been demonstrated to be correlated to poor prognosis in cancer and TANC2 was identified as a driver gene in cancer with effects on cell growth, survival and transformation." (PMID 35061901, 2022). "It would hence be of interest to look at the protein expression data in cancers for CTHRC1 and the now identified genes of interest, POSTN, MMP13, SFRP4, ADAMTS16 and FNDC1." (PMID 36190948, 2022). "Cytohubba analysis of these genes revealed 13 hub genes, of which MMP13, POSTN, SFRP4, ADAMTS16 and FNDC1 were significantly altered in their expression with CTHRC1 and seen to affect survival across cancers." (PMID 36190948, 2022). "Multiple members, including FNDC1, FNDC3A, and FNDC3B, demonstrated significant expression changes between cancer and surrounding normal tissue groups in the malignancies studied in this study." (PMID 36626432, 2022). "Our study in evaluating 1027 matrisome genes across cancers, has identified a novel set of genes (MMP13, FNDC1, SFRP4 and ADAMTS16) that could work with CTHRC1 to regulate cancer progression." (PMID 36190948, 2022). "Oncomine revealed that the mRNA expression levels of FNDC1, FNDC3A, and FNDC3B were higher in most malignancies than in normal tissues, but the mRNA expression levels of FNDC4, FNDC5, FNDC7, and FNDC8 were downregulated in most cancers when compared with normal tissues." (PMID 36626432, 2022). "The results showed that RGS2 and DUSP1 were significantly expressed in the cell population, and three model genes, CXCR4, SLCO2A1, and FNDC1, were not in the cluster, indicating that the two model genes that were significantly expressed could be used as marker genes of cancer." (PMID 36591293, 2022).
tumor (16 papers, 2018 to 2025). "Additional hub genes MMP13, SFRP4, ADAMTS16 and FNDC1 also significantly affect survival with their expression across tumour grades comparable to CTHRC1." (PMID 36190948, 2022). "After verification of these genes, 3 hub genes, namely CTHRC1, FNDC1, and INHBA, were found to be upregulated in tumor and associated with poor GC patient survival." (PMID 34968391, 2021). "Besides tumor regions, the FNDC1 peptide was also of high intensity across metastatic areas in lymph nodes and other secondary tumor sites, as lungs and abdominal masses." (PMID 34885011, 2021). "The upregulation of TLR3 (3.79×) and CD36 (2.73×), two general tumor markers, and SERPINEB9 (11.37×), FNDC1 (7.58×), and TACR2 (8.84×), three factors of tumorigenesis, confirms the wider pathological significance of this bacterium." (PMID 38787238, 2024). "Both peptides at m/z 867.513 and 1166.611, respectively assigned to FNDC1 and A1BG proteins, were significantly more intense in PD tumor over control regions (p = 0.0006 for m/z 867.513 and p = 0.0395 for m/z 1166.611)." (PMID 34885011, 2021). "In addition, MAGEC3 downregulates genes that are shown to induce tumor progression, including APLMR, FBLN5, and FNDC1." (PMID 35158998, 2022). "In conclusion, through comprehensive bioinformatics analysis, we successfully identified three hub genes (CTHRC1, FNDC1, and INHBA) that are differentially expressed between tumor and normal tissues in both TCGA-STAD and GSE66229 datasets and highly correlated with GC." (PMID 34968391, 2021). "The common upregulated genes in metastasis and primary tumor include epiphycan (EPYC), collagen type X alpha chain 1 (COL10A1), fibronectin type III domain containing 1 (FNDC1) and podocan-like protein I (PODNL1), which are mainly extracellular matrix related genes." (PMID 31600962, 2019).
FNDC1 also shares sentences with these, for which no sentence is quoted: Acute otitis media (2 papers); cardiovascular disease (2); lung carcinoma (2); ovarian carcinoma (2); and Central Nervous System cancer (1); aortic valve stenosis (1); bladder cancer (1); central nervous system lymphoma (1); cervical cancer (1); coronary heart disease (1); depression (1); diffuse gastric adenocarcinoma (1); ductal breast carcinoma in situ (1); essential hypertension (1); gastric adenocarcinoma (1); gastric intestinal type adenocarcinoma (1); Hepatic steatosis (1); hepatocellular carcinoma (1); Insulin resistance (1); invasive ductal breast carcinoma (1); Kawasaki disease (1); melanoma (1); metastatic disease (1); Obesity (1); pancreatic tumor (1); squamous cell lung carcinoma (1); uterine corpus endometrial carcinoma (1).